PNKD (PNKD metallo-beta-lactamase domain containing)
Description:
Probable thioesterase that may play a role in cellular detoxification processes; it likely acts on a yet-unknown alpha-hydroxythioester substrate (Probable). In vitro, it is able to catalyze the hydrolysis of S-D-lactoyl-glutathione to form glutathione and D-lactic acid at very low rate, though this reaction is not physiologically relevant in vivo.
Synonyms: MR-1; KIAA1184; MR1; TAHCCP2; FKSG19; DYT8; PDC; DKFZp564N1362; FPD1; BRP17; KIPP1184; MGC31943; PKND1; MR-1S; PNKD1; R1
Tractability: Antibody: UniProt places it where antibodies can reach, with high confidence; its Gene Ontology location is reachable by antibodies, with medium confidence. PROTAC: ubiquitination databases record sites on it; its protein half-life has been measured.
Gene: Protein-coding gene on chromosome 2 (218,269,651 to 218,346,793, forward strand). Ensembl gene ENSG00000127838.
Subcellular location: Cell membrane (Isoform 1); Mitochondrion; Cytoplasm (Isoform 2); Mitochondrion (Isoform 3); Golgi apparatus; Endoplasmic reticulum
Subcellular location (Human Protein Atlas): Mitochondria
Pathways (Reactome):
Metabolism: Complex IV assembly
Gene Ontology:
Molecular function: protein binding; hydroxyacylglutathione hydrolase activity
Biological process: negative regulation of neurotransmitter secretion; methylglyoxal catabolic process
Cellular component: cytoplasm; endoplasmic reticulum; Golgi apparatus; membrane; mitochondrion; plasma membrane; presynaptic cytosol
Genetic constraint (gnomAD): Loss-of-function variants: 33 observed, 39 expected, observed/expected ratio (o/e) 0.85, 90% interval 0.64 to 1.13. The upper end of that interval is the gene's LOEUF score, 1.13, which puts it in group 4 of 6, group 1 being the genes least tolerant of losing a copy. Missense variants: 469 observed, 473.73 expected, observed/expected ratio (o/e) 0.99, 90% interval 0.92 to 1.07. Synonymous variants: 173 observed, 190.56 expected, observed/expected ratio (o/e) 0.91, 90% interval 0.8 to 1.03.
Homologues: Orthologues: chimpanzee PNKD (99% identical), mouse Pnkd (96% identical), rat Pnkd (96% identical), guinea pig PNKD (96% identical), macaque PNKD (96% identical), rabbit PNKD (84% identical), dog PNKD (79% identical), pig PNKD (79% identical), tropical clawed frog pnkd (53% identical), zebrafish pnkd (50% identical), Drosophila melanogaster tzn (28% identical), Caenorhabditis elegans Y17G7B.3 (23% identical). Paralogues in human: HAGH (31% identical), HAGHL (28% identical), ETHE1 (16% identical), MBLAC2 (13% identical).
Diseases named in the same sentence as PNKD in open-access papers:
PNKD is named in the same sentence as 13 diseases in open-access papers, as found by Europe PMC text mining. Sharing a sentence is not in itself a finding about the gene and the disease. The quoted sentences say what the papers report.
breast carcinoma (2 papers, 2020 to 2022). "Arm-level deletion of PNKD was associated with breast cancer immune cell infiltration in BC." (PMID 36171887, 2022).
migraine (2 papers, 2020 to 2022). "Of note, hsa-miR-605-3p targets COL4A1, PNKD, TGFBR2, and YAP1, which have been identified as susceptible genes in migraine patients." (PMID 36704329, 2022).
episodic ataxia (1 paper, 2023). "Due to these nonepileptic events, molecular testing for episodic ataxia panel (CACNA1A, CACNB4, KCNA1, PNKD, PRRT2, SLAC1A3, VAMP1) was requested, and this came back normal." (PMID 37469362, 2023).
paroxysmal non-kinesigenic dyskinesia (1 paper, 2025). "The PNKD gene, also known as MR-1 (Myofibrillogenesis Regulator 1), is associated with paroxysmal non-kinesigenic dyskinesia (PNKD)." (PMID 40958306, 2025).
PNKD also shares sentences with these, for which no sentence is quoted: tumor (4 papers); cancer (3); infection (2); alcoholic cirrhosis (1); colorectal cancer (1); cryptococcosis (1); head and neck cancer (1); Obesity (1); ovarian carcinoma (1).